FCGR3A (Fc gamma receptor IIIa)
Description:
Receptor for the invariable Fc fragment of immunoglobulin gamma (IgG). Optimally activated upon binding of clustered antigen-IgG complexes displayed on cell surfaces, triggers lysis of antibody-coated cells, a process known as antibody-dependent cellular cytotoxicity (ADCC). Does not bind free monomeric IgG, thus avoiding inappropriate effector cell activation in the absence of antigenic trigger. Mediates IgG effector functions on natural killer (NK) cells. Binds antigen-IgG complexes generated upon infection and triggers NK cell-dependent cytokine production and degranulation to limit viral load and propagation. Involved in the generation of memory-like adaptive NK cells capable to produce high amounts of IFNG and to efficiently eliminate virus-infected cells via ADCC. Regulates NK cell survival and proliferation, in particular by preventing NK cell progenitor apoptosis. Following the engagement of antigen-IgG complexes, triggers phosphorylation of immunoreceptor tyrosine-based activation motif (ITAM)-containing adapters with subsequent activation of phosphatidylinositol 3-kinase signaling and sustained elevation of intracellular calcium that ultimately drive NK cell activation. The ITAM-dependent signaling coupled to receptor phosphorylation by PKC mediates robust intracellular calcium flux that leads to production of pro-inflammatory cytokines, whereas in the absence of receptor phosphorylation it mainly activates phosphatidylinositol 3-kinase signaling leading to cell degranulation. Costimulates NK cells and trigger lysis of target cells independently of IgG binding. Mediates the antitumor activities of therapeutic antibodies. Upon ligation on monocytes triggers TNFA-dependent ADCC of IgG-coated tumor cells. Mediates enhanced opsonization and ADCC in response to afucosylated IgGs. (Microbial infection) Involved in Dengue virus pathogenesis via antibody-dependent enhancement (ADE) mechanism. Secondary infection with Dengue virus triggers elevated levels of afucosylated non-neutralizing IgG1s with reactivity to viral envelope/E protein. Viral antigen-IgG1 complexes bind with high affinity to FCGR3A, facilitating virus entry in myeloid cells and subsequent viral replication.
Synonyms: FcRIIIa; FcgammaRIIIA; CD16a; FCG3; FCGR3; IGFR3; CD16; FcGRIIIA; CD16-II; IMD20
Tractability: Small molecule: a structure with a bound ligand is known. Antibody: a drug acting on it is in phase 2 or 3 trials; UniProt places it where antibodies can reach, with high confidence; its Gene Ontology location is reachable by antibodies, with high confidence; UniProt predicts a signal peptide or a membrane-spanning region. PROTAC: its protein half-life has been measured.
Target class: Membrane receptor
Gene: Protein-coding gene on chromosome 1 (161,541,759 to 161,550,968, reverse strand). Ensembl gene ENSG00000203747.
Subcellular location: Cell membrane; Secreted
Pathways (Reactome):
Immune System: FCGR activation; Immunoregulatory interactions between a Lymphoid and a non-Lymphoid cell; Regulation of actin dynamics for phagocytic cup formation; Role of phospholipids in phagocytosis
Disease: FCGR3A-mediated IL10 synthesis; FCGR3A-mediated phagocytosis
Gene Ontology:
Molecular function: immune receptor activity; low-affinity IgG receptor activity; protein binding; IgG receptor activity
Biological process: antibody-dependent cellular cytotoxicity; calcium-mediated signaling; Fc-gamma receptor signaling pathway; macrophage activation; natural killer cell activation; natural killer cell degranulation; natural killer cell mediated cytotoxicity; phosphatidylinositol 3-kinase/protein kinase B signal transduction; positive regulation of natural killer cell proliferation; positive regulation of tumor necrosis factor production; cell surface receptor signaling pathway; immune response
Cellular component: external side of plasma membrane; extracellular exosome; extracellular region; Fc-gamma receptor III complex; plasma membrane
Genetic constraint (gnomAD): Loss-of-function variants: 15 observed, 22.82 expected, observed/expected ratio (o/e) 0.66, 90% interval 0.44 to 1.01. The upper end of that interval is the gene's LOEUF score, 1.01, which puts it in group 4 of 6, group 1 being the genes least tolerant of losing a copy. Missense variants: 235 observed, 273.33 expected, observed/expected ratio (o/e) 0.86, 90% interval 0.77 to 0.96. Synonymous variants: 93 observed, 103.74 expected, observed/expected ratio (o/e) 0.9, 90% interval 0.76 to 1.07.
Homologues: Orthologues: macaque FCGR3 (92% identical), rabbit FCGR3A (61% identical), mouse Fcgr4 (61% identical), rabbit FCGR3B (61% identical), rat Fcgr3a (59% identical). Paralogues in human: FCGR3B (89% identical), FCGR2A (42% identical), FCGR2B (40% identical), FCGR2C (39% identical), FCGR1A (36% identical), FCER1A (35% identical), FCRLB (30% identical), FCRL5 (29% identical), FCRL3 (23% identical), FCRL4 (23% identical), FCRLA (21% identical), PECAM1 (20% identical), and 5 more.
Diseases named in the same sentence as FCGR3A in open-access papers:
FCGR3A is named in the same sentence as 197 diseases in open-access papers, as found by Europe PMC text mining. Sharing a sentence is not in itself a finding about the gene and the disease. The quoted sentences say what the papers report.
COVID-19 (31 papers, 2020 to 2025). A disease caused by infection with severe acute respiratory syndrome coronavirus 2. "(I) The proportion of FCGR3A (CD16)-positive cells within the CD4+ and CD8+ T cell populations in BALF from HC and COVID-19 patients, with the FCGR3A expression threshold set at 0.5." (PMID 38607373, 2024). "Since the FCgamma receptor signaling pathway is triggered by FCGR1A/2A/3A, we analyzed the expression of FCGR3A (CD16) in monocytes from our COVID-19 patient cohort." (PMID 37869162, 2023). "In order to improve and simplify the efficacy of prediction and diagnosis of CU, especially COVID-19-related CU, we identified three key genes (FCGR3A, CCL3, and TNF) from hub genes by the machine learning LASSO regression analysis." (PMID 36531995, 2022). "This is supported by a high expression of FCGR3A, encoding CD16, in the BAL fluid NK cells of patients with severe COVID-19 as it indicates a high frequency of CD56dimCD16+ NK cells." (PMID 35371005, 2022). "Six hub genes (FCGR3A, CD69, IFNG, CCR7, CCL5, and CCL4) were closely associated with COVID-19 and HF." (PMID 36420258, 2022). "Our research further displayed that all the key genes (CCL3, TNF, and FCGR3A) were statistically related to central infiltration cells (e.g. mast cells and macrophages M0) in CU and COVID-19." (PMID 36531995, 2022). "The molecular explanation for the decreased transplacental transfer of IgG in antenatal COVID-19, including whether the trophoblast Fc glycosylation and FCGR3A expression have a role, remains to be explored." (PMID 38400147, 2024). "On the other hand, non-classical monocytes (and their marker FCGR3A) were decreased in COVID-19, which is also consistent with recent studies." (PMID 35064122, 2022). "Six hub genes (FCGR3A, CD69, IFNG, CCR7, CCL5, and CCL4) were involved in regulating immune cells in COVID-19 and HF, which may contribute to the pathogenesis of HF." (PMID 36420258, 2022). "To sum up, FCGR3A, TNF, and CCL3 might be potential biomarkers for COVID-19-related CU, and the common pathways and related molecules we explored in this study might provide new ideas for further mechanistic research." (PMID 36531995, 2022). "These indicated that FCGR3A, TNF, and CCL3 might be the key genes of COVID-19-related CU." (PMID 36531995, 2022). "Indeed, FCGR3A has been already found to be a nonclassical monocyte marker in COVID-19." (PMID 36806094, 2023).
systemic lupus erythematosus (25 papers, 2004 to 2026). An autoimmune multi-organ disease typically associated with vasculopathy and autoantibody production. "We highlighted an association between the FCGR3B-NA1/NA1 and FCGR3A-158F alleles and systemic lupus erythematosus, in addition to an association between FCGR2A-131R and lupus nephritis." (PMID 40728959, 2025). "Mutations in the FCGR3A gene are linked to recurrent viral infections, susceptibility to systemic lupus erythematosus, and alloimmune neonatal neutropenia." (PMID 35668930, 2022). "FCGR2A/FCGR3A has been reported to be a susceptibility gene for other autoimmune diseases, such as systemic lupus erythematosus, rheumatoid arthritis, multiple sclerosis, type 1 diabetes and ulcerative colitis." (PMID 27769046, 2017). "Among these IgG Fc receptors, Fcgr3a has been described as a susceptibility factor for autoimmune diseases such as systemic lupus erythematosus and rheumatoid arthritis." (PMID 18045489, 2007). "We did find association of the FCGR3A*T allele with the lupus phenotype in White American patients in our cohort relative to a geographically and ethnically matched population (OR = 1.24, 95%CI: 1.01–1.52; p = 0.024)." (PMID 17076550, 2006). "Mutations and aberrant expression of FCGR3A have been reported to contribute to increased susceptibility to several inflammatory and immune diseases, including systemic lupus erythematosus, recurrent infectious diseases, and childhood chronic immune thrombocytopenic purpura." (PMID 37024561, 2023). "Interestingly, the evaluation of FCGR3A variants demonstrated different genetic association for the global lupus phenotype and for the renal involvement (FCGR3A∗T and FCGR3A∗GG, resp)." (PMID 26798662, 2015). "Furthermore, we have shown, to our knowledge for the first time, that a polymorphism of FCGR3A (FCGR3A*GG) predisposes lupus patients with renal involvement to the occurrence of ESRD over and above other socioeconomic–demographic and clinical variables included in the model." (PMID 17076550, 2006). "Having only 1 copy of FCGR3A has been associated with lower ADCC activity of NK cells and with clinical conditions, e.g., sarcoidosis and systemic lupus erythematosus (SLE)." (PMID 40411624, 2025). "When we examined the effect of genetic control on sex-DEGs, we found genetic variants affecting the female-biased expression of FCGR3A in natural killer (NK) cells (rs2099684) and ITGB2 in monocytes (rs760462), both of which are associated with systemic lupus erythematosus." (PMID 42102734, 2026). "We compared the frequencies of the functional SNPs of FCGR2A (FcγRIIa-H131R, rs1801274), FCGR2B (FcγRIIb-I232T, rs1050501), FCGR3A (FcγRIIIa-V158F, rs396991) and FCGR3B variants (FcγRIIIb NA1 and NA2) between lupus and healthy controls in an indigenous African Caribbean population." (PMID 40728959, 2025). "In searchable articles reports, most of studies on FCGR3A (CD16a) have focused on the pathogenesis, diagnosis, and treatment of inflammatory diseases such as IgG immune complexes (including rheumatoid arthritis and systemic lupus erythematosus), and little attention has been paid to cancer." (PMID 35668930, 2022). "In particular, single nucleotide polymorphisms (SNPs) in FCGR2A (R131H), FCGR2B (I232T) FCGR3A (V158F) and FCGR3B (NA1/NA2), have been reported in association with systemic lupus erythematosus (SLE), rheumatoid arthritis (RA) and/or idiopathic thrombocytopenia purpura (ITP)." (PMID 20957197, 2010). "For example, FCGR3A, FCGR2B and HLA-DQA1 may function via the systemic lupus erythematosus pathway, and AMY2B and AMY2A may participate in lung SCC via starch and sucrose metabolism pathway." (PMID 26297502, 2015). "Furthermore, FCGR3A SNPs are clinically relevant in infections such as malaria, severe COVID-19, bacteremia in transplant patients, periodontitis, as well as in Kaposi’s sarcoma in HIV-infected patients and autoimmune diseases, including lupus and rheumatoid arthritis." (PMID 39051331, 2024).
viral infection (25 papers, 2014 to 2025). "Decreased expression of FCGR3A/B, which are IgG receptors of NK cells and polymorphonuclear neutrophils, is implicated in antibody-dependent enhancement of viral infections." (PMID 38778280, 2024). "Similar to FCGR2B, genetic variants in the FCGR3A gene have been associated with SLE47, as well as immunodeficiency, susceptibility to recurrent viral infections, and alloimmune neonatal neutropenia." (PMID 39990346, 2025). "Studies have shown that flaviviruses like ZIKV and DENV exploit Fc-mediated pathways to enhance viral infection, emphasizing the potential role of FCGR3A in viral pathogenesis." (PMID 40430433, 2025). "Our analysis extends these findings to OROV, identifying FCGR3A (CD16a) as a potential antiviral target, aligning with prior work on immune modulation in viral infections." (PMID 40430433, 2025). "One of the genes encoding FcγRIII (FCGR3A) was elevated in MIS-C, bacterial infection and KD in comparison with viral infection." (PMID 39300098, 2024). "Cluster 3 (FCGR3A+) was enriched for IFITM3 and FCGR3A, related to the interferon response, inhibition of viral replication and ability to kill target cells after viral infection." (PMID 37078407, 2023). "FCGR3A, also named CD16, was linked to patient susceptibility to recurrent viral infections, and its gene polymorphisms were related to patient susceptibility to BD." (PMID 36959847, 2023). "Increased expression was also observed for the cell-surface phagocytosis receptor, Fcgr3a, and genes linked to autophagy (Atg12, Snx4), antigen presentation pathway (RT1-CE6), Itm2a, involved in immunoglobulin production, and Oas1g, an immune response protein against viral infection." (PMID 34587117, 2021). "Four subsets strongly expressed KLRF1 and FCGR3A, displayed surface expression of CD161 and resembled a population of CD16+ CD8+ T cells that has previously been described in other viral infections." (PMID 36591270, 2022).
breast carcinoma (22 papers, 2011 to 2025). "So far, no previous study has reported data for the relationship between FCGR3A-V158F rs396991 polymorphism and response to trastuzumab among Egyptian patients with breast cancer." (PMID 39472454, 2024). "Previous studies have shown that genetic polymorphism of them FCGR3A-V158F rs396991 may affect the response to trastuzumab treatment in HER2-positive breast cancer patients." (PMID 39472454, 2024). "Secondly, the presence of other associated polymorphisms of the FCGR3A gene could affect the comprehensiveness and preciseness of the relationship between FCGR3A-V158F polymorphisms and clinical outcomes in breast cancer patients on trastuzumab-based therapy." (PMID 39472454, 2024). "Our study investigated the relationship between the FCGR3A-V158F polymorphism and the clinicopathological characteristics of breast cancer patients, including age, family history, TNM staging, tumor size, lymph nodes, histopathological grade, and hormonal receptor status." (PMID 39472454, 2024). "Indeed, patients carrying the allelic variants of FCGR2A, FCGR2C, and FCGR3A which exhibit increased affinity for human IgG demonstrated better responsiveness to anti-tumor antibody therapy in cases of B cell lymphomas, colorectal, renal, and breast cancers." (PMID 35372055, 2022). "Our study aimed to investigate the association of FCGR3A-V158F gene polymorphism with breast cancer and to evaluate the impact of FCGR3A-V158F gene polymorphism on trastuzumab response in HER2-positive breast cancer patients." (PMID 39472454, 2024). "In this study, we evaluated the association between FCGR3A-V158F gene polymorphism and response to trastuzumab in HER2-positive breast cancer patients." (PMID 39472454, 2024). "Accordingly, this study aims investigate the association between FCGR3A-V158F gene polymorphism and response to trastuzumab in HER2-positive breast cancer patients." (PMID 39472454, 2024). "And FCGR3A has potential clinical relevance in the treatment of breast cancer." (PMID 36797662, 2023). "Several studies concerning FCGR polymorphisms and efficacy of trantuumab and rituximab demonstrated that FCGR2A H131R and FCGR3A V158F could predict clinical efficacy and survival of patients with breast cancer and lymphoma, respectively." (PMID 26363448, 2015). "The aim of the study was to validate the association between the Arg166His polymorphisms of the Fc immunoglobulin receptor 2A (FCGR2A) and the Val212Phe of FCGR3A and pathological clinical response (pCR) to trastuzumab in HER2-positive breast cancer patients." (PMID 28983344, 2015). "Further, in a sample of 15 operable and 35 metastatic HER2-positive breast cancer patients, FCGR2A His/His predicted the response to trastuzumab in neoadjuvant chemotherapy and in metastatic setting, while FCGR3A Val/Val did not." (PMID 28983344, 2015).
rheumatoid arthritis (19 papers, 2005 to 2025). A chronic, systemic autoimmune disorder characterized by inflammation in the synovial membranes and articular surfaces. "This meta-analysis revealed an association between FCGR3A V158 and an increased risk of immune thrombocytopenia and rheumatoid arthritis." (PMID 41000382, 2025). "Regarding FCGR3A, it has been functionally implicated in rheumatoid arthritis (RA), where circulating and synovial immune complexes have been shown to activate FCGR3A, supporting its pathogenic role in immune complex-driven inflammation." (PMID 40918143, 2025). "Statistically significant associations were also found between rheumatoid arthritis and FCGR3A F158V polymorphisms (recessive: OR = 1.36, 95% CI 1.09-1.69, for VV vs. FF + FV, and allele comparison: OR = 1.15, 95% CI 1.03-1.29, for V vs. F, in the overall analyses)." (PMID 41000382, 2025). "FCGR3A gene is associated with the risk of lesions in several oncological diseases, for example, FCGR3A gene polymorphisms are positively associated with the risk of lesions in colorectal cancer, and genetic variants of FCGR3A are associated with drug resistance in rheumatoid arthritis." (PMID 36505767, 2022). "The data in rheumatoid arthritis (RA) are conflicting and we previously demonstrated an association between FCGR3A and RA." (PMID 16356189, 2006). "Abatacept is an immunosuppressant, which is used for the treatment of rheumatoid arthritis, psoriatic arthritis, and juvenile idiopathic arthritis, and FCGR3A can affect the response to abatacept treatment in rheumatoid arthritis." (PMID 40561275, 2025). "Previous studies have shown that FCGR3A is involved in immune responses and inflammation, and its expression is upregulated in various autoimmune and inflammatory diseases, such as rheumatoid arthritis and lupus erythematosus." (PMID 36936436, 2023). "In summary, this meta-analysis found FCGR3A V158 to be associated with an increased susceptibility to two autoimmune diseases, namely immune thrombocytopenia (ITP) and rheumatoid arthritis (RA)." (PMID 41000382, 2025).